CXCL14 (C-X-C motif chemokine ligand 14)
Diseases named in the same sentence as CXCL14 in open-access papers (continued):
Sharing a sentence is not in itself a finding about the gene and the disease.
cancer (continued). "In addition, CXCL14 present on blood vessels in dermal plexus may be associated with its antiangiogenic effect in cancers." (PMID 26733763, 2016). "CXCL14 is reported to play dual roles in cancer progression, and both its antitumor role and protumor role depend on the cancer type and source." (PMID 40898244, 2025). "Ki67 and cleaved-caspase 3 immunohistochemical staining indicated increased apoptosis and decreased proliferation of cancer cells following cisplatin treatment upon blockade of the CXCL14/CCR7/STAT3/ERCC4 axis." (PMID 40898244, 2025). "Lactate produced by chemoresistant cancer cells not only enhances fibroblast activation and CXCL14 expression but also establishes a positive feedback loop that drives the development of chemoresistance within the TME." (PMID 40898244, 2025). "CXCL14 secreted by CAFs stimulates the pro-tumor activity of CAFs and also acts on cancer cells, enhancing their proliferation." (PMID 40136652, 2025). "Immunohistochemistry showed that key markers identifying this putative Tr-CAF subset—CXCL14, ADAMDEC1, EDNRB, and PROCR—were predominantly localized to fibroblasts within normal colonic mucosa and less frequently in cancer-associated fibroblasts (CAFs)." (PMID 40759242, 2025). "To better understand the purview of CXCL14 functions and potential interactions with biological pathways in cancer progression, we performed gene-to-function analyses using Ingenuity Pathway Analysis (IPA)." (PMID 38400076, 2024). "Overall, our findings from the pathway analysis provide insights into the future directions of investigating the role of CXCL14 in antitumor immunity and cancer progression." (PMID 38400076, 2024). "The CALB2-Ca2+-CXCL14 inflammatory axis confers highly metastatic capability upon cancer cells and further facilitates an inflammatory and immunosuppressive TME in PDAC." (PMID 39358777, 2024). "CALB2-Ca2+-CXCL14 inflammatory axis confers highly metastatic and immunosuppressive ability on cancer cells." (PMID 39358777, 2024). "Our and others’ studies strongly suggest that CXCL14 plays an important role in activating antitumor immunity in multiple cancers, including HPV+ HNSCC." (PMID 38400076, 2024). "Here, we provide updates on the role of CXCL14 in cancer progression and discuss the potential development and application of CXCL14 as an immunotherapeutic agent." (PMID 38400076, 2024). "In contrast, the increased expression of CXCL14/17 indicated positive correlation with cancer stage, patients’ age, weight and menopause status." (PMID 38232115, 2024). "The c04_CXCL12 subgroup displayed characteristics of both antigen‐presenting cancer‐associated fibroblasts (apCAFs), marked by CD74 and HLA‐DRA, and immune‐related cancer‐associated fibroblasts (iCAFs), indicated by CXCL14 and CXCL12." (PMID 39716897, 2024). "While more research is required on CXCL14, its multifaceted role in numerous cancers, including PDAC, and its unique structure make it worth discussing." (PMID 38339310, 2024). "Other groups have also shown the effectiveness of decitabine in upregulating CXCL14 to treat cancer." (PMID 38400076, 2024). "This suggests that, in addition to enhancing the cancer cell invasive capabilities, CXCL14 can also help facilitate macrophage infiltration in tumors, possibly leading to increased TAM accumulation." (PMID 38339310, 2024). "Pan-cancer analysis indicated that the CXCL14 was differentially expressed in most cancers and corresponding normal tissue, indicating its widespread effect on cancer development." (PMID 37563546, 2023). "In head and neck squamous cell carcinoma and colorectal cancer, CXCL14 suppresses cancer cell migration and invasion." (PMID 37056937, 2023). "CXCL14 is the significant differential gene, which has an emerging immune and inflammatory modulator mediated cancer response." (PMID 36893166, 2023). "Proteins including CXCL14, GDF15, HAVCR1, and CDCP1 were identified as predominant contributors to the risk of cancer." (PMID 38016990, 2023).
cancer (continued). "As an exogenous substance, the specific anti-cancer mechanism of the yak CXCL14 protein remains to be further studied." (PMID 37835641, 2023). "H1299 (Vector), CXCL14-OV, and CXCL14-KD were orthotopically implanted in the left lung and cancer metastasis was analyzed using an in vivo imaging system (IVIS)." (PMID 37056937, 2023). "Although the potential role of CXCL14 in cancer has been a focus of research in recent years, other aspects of CXCL14 are also being explored." (PMID 37215496, 2023). "The chemokine CXCL14 is a key regulatory factor in cancer and a potential target for future cancer immunotherapy." (PMID 37880315, 2023). "Chemokine CXCL14 is a key regulatory factor in cancer and represents a potential target for future cancer immunotherapies." (PMID 35517862, 2022). "The percentages of high CXCL14 expression in stromal fibroblasts and cancer cells were 57% (69/121) and 29.3% (39/133), respectively." (PMID 35769715, 2022). "As an important chemokine, the role of CXCL14 displays a cancer-type-dependent pattern, including either oncogenic or antitumor roles." (PMID 35669852, 2022). "Although CXCL14 as an orphan chemokine is poorly understood, most recently, CXCL14 has been posited as an immune mediator in many cancer types." (PMID 36012586, 2022). "CXCL9, CXCL10, CXCL11, CXC12, CXCL13, and CXCL14 expression in the tissue adjacent to carcinoma was significantly different." (PMID 35181719, 2022). "Accumulating evidence has demonstrated the multifarious roles of CXCL14 in cancer progression and immune responses." (PMID 34744744, 2021). "A study has investigated the abnormal expression of CXCL14 and its biological functions in diverse carcinomas." (PMID 34789307, 2021). "Herein, we demonstrated that the CXCL14 level was elevated in carcinoma tissues as compared with para-cancerous tissues." (PMID 34789307, 2021). "Such a function of fibroblast targeting CXCL14 loops has been reported for other cancers with profound microenvironment like breast cancer, but data on PDAC on this topic are missing." (PMID 31561620, 2019). "In this report, we review recent studies on the identification and characterization of CXC ligand 14 (CXCL14) in cancer progression and provide an analysis of future perspectives in this research field." (PMID 31014014, 2019). "Further studies are needed to investigate the relationship between the levels of blood CXCL14 and cancer incidence." (PMID 31014014, 2019). "In transgenic mice overexpressing CXCL14, the rate of chemical carcinogenesis, the growth of transplanted tumors, and experimental metastasis of carcinoma cells were all suppressed." (PMID 31014014, 2019). "A recent study showed that these myeloid cells are recruited by the cancer cell-derived, angiostatic chemokine, CXCL14, which instigated PI3K signaling in these myeloid cells." (PMID 29371595, 2018). "We and other groups have shown antitumor activity of CXCL14 in cancers of the lung, head and neck, colon, and liver." (PMID 29438328, 2018). "It is increasingly recognised that CXCL14 and other EMT mediators are often derived from cancer-associated fibroblasts (CAFs) and function in a paracrine manner." (PMID 30202034, 2018). "As a consequence CXCL14 promotes cancer cell motility through elevated cytosolic Ca2+ released from the endoplasmic reticulum (ER) mediated through interaction between CXCL14 and inositol 1,4,5-trisphosphate receptor on the ER." (PMID 26733763, 2016). "Since a lot of research over years has been done to study CXCL14 mediated effects in cancer, its expressional regulation has been explored in several types of carcinomas." (PMID 26733763, 2016). "CXCL14 is a novel chemokine, and mainly stimulating cell migration that involved with immune surveillance, inflammation and cancer." (PMID 27769059, 2016). "Restoration of Cxcl14 expression in HPV-positive cancer cells clears tumors in immunocompetent syngeneic mice, but not in immunodeficient mice." (PMID 27143385, 2016).
cancer (continued). "To examine CXCL14 promoter hypermethylation in HPV-positive cancer tissues, we analyzed CXCL14 DNA methylation data from 279 HNC and 309 CxCa tissue samples obtained from the TCGA database." (PMID 27143385, 2016). "We report that, while many proinflammatory chemokines increase expression throughout cancer progression, CXCL14 is dramatically downregulated in HPV-positive cancers." (PMID 27143385, 2016). "Consistent with our results from cervical tissue specimens, the cervical keratinocyte lines W12E, W12G, and W12GPXY showed gradually increasing levels of CXCL14 promoter hypermethylation during cancer progression." (PMID 27143385, 2016). "The incidence of AOM/DSS-induced cancer in the CXCL14 Tg mice was significantly lower (P < 0.001) than that observed for the Wt ones." (PMID 25765541, 2015). "These previous findings were consistent with our results and provided important evidences of the roles which CXCL14 played in the cancer progression." (PMID 25760073, 2015). "The MB-downregulated genes include cancer-associated cytokines/chemokines (e.g. CXCL1, CXCL2, CXCL3, CXCL14, IL1A, IL1B, IL6, IL8) and matrix metalloproteinases (MMP1,MMP9)." (PMID 25642713, 2015). "In contrast, CXCL14 expressed by cancer cells inhibits the growth of xenograft tumors derived from different origins." (PMID 24734219, 2014). "SPARC, RECK, TNFAIP3 and CXCL14 were down-regulated (p < 0.05) in BCBM as compared to primary BC samples irrespectively of the cancer subtype, while for CADM1, this correlation was found in HR positive and TNBC samples." (PMID 24833255, 2014). "The role of CXCL14 in cancer development is complex and contradictory." (PMID 39358777, 2024). "Our findings suggest that CXCL14 is critical for the antitumor control of HPV+ cancers." (PMID 38400076, 2024). "The effect of CXCL14 on metastasis has previously been observed in other cancer types." (PMID 38400076, 2024). "Interestingly, a CXCL14-based peptide has previously been suggested as a potential cancer treatment." (PMID 38200223, 2024). "We and others have revealed that the chemokine CXCL14 promotes antitumor immune responses, suggesting that CXCL14 may be effective for cancer immunotherapy." (PMID 38400076, 2024). "Based on the antitumor activity of CXCL14 through immune activation in several cancers, we propose that CXCL14 could be used in cancer immunotherapy, particularly in treating HPV+ cancers." (PMID 38400076, 2024). "The level of CXCL14 expression was higher in the cancer cells." (PMID 37056937, 2023). "For cancer, CXCL14 showed the greatest predictive importance." (PMID 38016990, 2023). "Multiple studies have explored the role of CXCL14 in cancers." (PMID 37563546, 2023). "This study aims to determine the mechanism of CXCL14-promoted cancer metastasis." (PMID 37056937, 2023). "Across studies, the results are inconsistent regarding the association between CXCL14 expression and cancer survival, and further, this has not been investigated in EC specifically." (PMID 37688629, 2023). "The elimination of ACKR2 decreases the migration of CXCL14-induced cancer cells." (PMID 37056937, 2023). "CXCL14 is ambiguous and disparate in different types of cancers." (PMID 37056937, 2023). "In particular, ACKR2 knockdown abolished CXCL14-induced cancer cell motility." (PMID 37056937, 2023). "CXCL14 was found elevated in colorectal, ovarian, prostate, and breast cancers." (PMID 36868311, 2023). "Cancer-associated fibroblasts (CAFs) can inhibit both the innate and adaptive antitumor immune response by secreting numerous chemokines and cytokines, such as TGF-β, IL-6, IL-8, IL-13, CXCL12, CXCL14, and VEGFA." (PMID 35646893, 2022). "In cancer tissues, all subgroups of CXCL14+INHBA+ fibroblasts were highly increased." (PMID 36463319, 2022). "The aberrant expression profile of CXCL14 has also been reported in several cancers." (PMID 35669852, 2022). "Additionally, CXCL14-recruited/polarized M2 TAMs facilitate cancer cell intravasation and metastasis." (PMID 35439170, 2022).
cancer (continued). "To study whether CXCL14 participates in cancer immunotherapy by NK cells, we first knocked down or overexpressed CXCL14 using lentivirus in NK cells." (PMID 33733587, 2021). "Consistently, the levels of CXCL14 expression are reduced in these and other cancers." (PMID 29438328, 2018). "The developmental role for CXCL12 and CXCL14 chemokines in CT differentiation is fully consistent with their recognised functions in adult fibrosis processes, such as in chronic fibrotic pathologies and cancer-induced fibrosis." (PMID 29222527, 2017). "CXCL14 mRNA expression was progressively decreased by about 21-fold from normal to cancer tissue." (PMID 27143385, 2016). "Of interest, a post-translational mechanism for the loss of CXCL14 protein is reported in cancer and immortalized cell lines, but not in normal epithelial cells, which is regulated through ubiquitin-mediated, the 26 S proteasome participated degradation." (PMID 26733763, 2016). "Additionally, by directly binding to IL-8, CXCL14 inhibits the ability of IL-8 to recruit endothelial cells and promote angiogenesis, which is known to be essential for cancer progression." (PMID 27143385, 2016). "To determine whether CXCL14 downregulation is unique to HPV-positive cancers, we compared CXCL14 mRNA expression between HPV-positive and HPV-negative HNCs using the data sets from our previous global gene expression study." (PMID 27143385, 2016). "Like CXCL14, FAP expression has been associated with cancer-associated fibroblasts." (PMID 26893359, 2016). "Furthermore, almost all the cancer cells in the lymph node metastases were also CXCL14-immunopositive." (PMID 23294544, 2013). "Additionally, the number of CXCL14-positive cancer cells increased as cancer cells invaded deeply, with more than 90% of the cells in the regions of the muscularis propria and subserosa immunopositive." (PMID 23294544, 2013). "Furthermore, the majority of the cancer cells in the lymph node metastases were also CXCL14-immunopositive." (PMID 23294544, 2013). "The involvement of ACKR2 in CXCL14-triggered signaling pathways, such as phospholipase Cβ3, protein kinase Cα, and proto-oncogene tyrosine-protein kinase Src, which subsequently upregulate nuclear factor kappa B transcriptional activity, leads to cancer cell EMT and migration." (PMID 40786043, 2025). "However, it is still unknown what mechanism governs CXCL14-mediated antitumor activity, how to deliver CXCL14, what dose to apply, and what combinations with existing therapy may boost antitumor immune responses in cancer patients." (PMID 38400076, 2024). "These parameters include, first of all, the CXCL14/CEA and CXCL16/CEA indexes, which showed extremely high diagnostic usefulness and the possibility of assessing and differentiating between CRC and healthy volunteers, as well as between the stages of cancer advancement." (PMID 37240636, 2023). "However, the mechanism of CXCL14 is attracting increasing attention because abnormal expression of CXCL14 could play an important role in several cancers." (PMID 37056937, 2023). "However, the pathway of cancer cell apoptosis, when induced by CXCL14, could be related to nuclear apoptosis and mitochondrial apoptosis." (PMID 37835641, 2023). "On the other hand, CXCL14 may be a prospective target for cancer treatment." (PMID 35842899, 2022). "It has been suggested that CXCL14 may play important roles in angiogenesis inhibition and in promoting the recruitment of antigen-presenting cells (APCs), natural killer (NK) cells, and T cells, thereby preventing HPV-associated cancer progression." (PMID 31428574, 2019). "Thus, the discovery or development of an edible small molecule that stimulates CXCL14 expression in the human body may be a useful and cost-effective method of cancer prevention." (PMID 31014014, 2019). "Thus, reversing the promoter hypermethylation of CXCL14 could be a feasible approach for restoring antitumor immune responses to treat HPV-positive cancers." (PMID 27143385, 2016).